AFP (alpha fetoprotein)
Diseases named in the same sentence as AFP in open-access papers (continued):
Sharing a sentence is not in itself a finding about the gene and the disease.
tumor (continued). "The univariate COX analysis indicated that the pathological stage, tumor size, serum AFP level, and PFDN6L expression were significant prognostic factors for the 5-year survival of HCC patients." (PMID 41425729, 2025). "Regular imaging, tumor marker surveillance (e.g., alpha-fetoprotein and beta-human chorionic gonadotropin), and cardiac function assessments are essential components of follow-up care." (PMID 40429559, 2025). "Tumor assessment after the 2nd and 4th cycles indicated partial response (PR), and after 6 cycles, a complete response (CR) was achieved, with AFP remaining normal." (PMID 41561743, 2025). "A multicenter study incorporating tumor size, the number of tumors, and AFP levels in the model achieved a prognostic predictive value of approximately 70%." (PMID 40486884, 2025). "The most commonly used serum tumor markers in BCa screening and auxiliary diagnosis include AFP, CEA, CA153, CA152, and CA199." (PMID 40158122, 2025). "The suppression of tumor growth was also reflected by histological staining and a significant decrease in the serum α-fetoprotein (AFP) level." (PMID 41392988, 2025). "This study aimed to determine how these different tobacco use patterns influence tumor markers, including AFP, CA 19-9, CEA, and PSA." (PMID 40078230, 2025). "Tumor markers, including alpha-fetoprotein (AFP), lactate dehydrogenase (LDH), and beta-human chorionic gonadotropin (β-HCG), were all within normal limits." (PMID 41220451, 2025). "We observed differential expression of DBF4B in several subgroups of clinical features, including pathological stage, tumor status, race, weight, histological type, histological grading, AFP, and vascular invasion." (PMID 40535802, 2025). "Promising biomarkers include lens culinaris agglutinin-reactive AFP, des-gamma-carboxy prothrombin, methylated DNA markers, plasma microRNA expression, circulating tumor DNA, and circulating tumor cells." (PMID 40322566, 2025). "Serum tumor markers (AFP and β-hCG) also showed substantial post-treatment declines, corresponding with clinical improvement." (PMID 40429559, 2025). "Emerging biomarkers such as GALAD (Gender, Age, Lens culinaris agglutinin-reactive AFP (AFP-L3), AFP, and Des-gamma-carboxyprothrombin) and circulating tumor DNA (ctDNA) are currently being extensively explored." (PMID 40918463, 2025). "These AFP results indicate that overall tumor burden was reduced more effectively with PD-1 + 125I therapy than with PD-1 alone, aligning with the imaging findings." (PMID 41357510, 2025). "Tumor marker examination results included: AFP 2.9 (0–7 ng/mL), CEA 2.03 (0–6.5 ng/mL), ferritin 248.00 (30–400 ng/mL), CA199 9.16 (0–27 U/mL), NSE 21.90 (0–16.3 ng/mL), CF21-1 4.42 (0–3.3 ng/mL), CA125 104.00 (0–35 U/mL)." (PMID 40313546, 2025). "No statistical differences were observed in gender, age, serum AFP level, tumor location, depth of invasion, pTNM stage, tumor size, lymph node metastasis, nerve invasion, vascular invasion, and differentiation degree among the histologic subtypes." (PMID 39928247, 2025). "Immunohistochemistry demonstrated positivity of the malignant yolk sac component for SALL4 (Sal-like protein 4), Glypican-3, and AFP, which confirmed yolk sac tumor differentiation." (PMID 41281142, 2025). "Another study reported the MELDEQ, in which the combination of the MELD score, AFP, tumor number, and tumor dimensions was reported." (PMID 40427217, 2025). "At the 1-month follow-up, tumor marker tests revealed an AFP level of 1,687.8 ng/ml (reference range: 0.0–2,000 ng/ml) and a NSE level of 33.8 ng/ml (reference range: 21–39.2 ng/ml)." (PMID 40980129, 2025). "The most clinically valuable tumor markers include alpha-fetoprotein (AFP), beta-human chorionic gonadotropin (β-hCG), lactate dehydrogenase (LDH), cancer antigen 125 (CA 125), and inhibin." (PMID 40723200, 2025). "By regulating stem cell characteristics, immune escape, and remodeling the tumor microenvironment, AFP forms a pro-tumor network." (PMID 40458724, 2025).
tumor (continued). "The easily applicable ATSI score based on the baseline AFP level and initial tumor shape can effectively predict efficacy and survival in HCC patients with ICIs." (PMID 39714631, 2025). "To further validate the clinical utility of the model, we constructed a decision curve analysis (DCA) to compare the prognostic performance of the MRPL family model with that of other established tumor biomarkers, including AFP, MKI67, and KRT19." (PMID 41399509, 2025). "While studies in other malignancies suggest that tumor markers can help support a diagnosis of pseudoprogression, the utility of AFP and protein induced by vitamin K absence-II (PIVKA-II) in HCC is not yet well established." (PMID 40726876, 2025). "Conventional tumor markers, such as AFP and DCP, have been widely reported as useful indicators for evaluating treatment response and prognosis in HCC." (PMID 40940925, 2025). "The Ensemble-DL signature had a greater impact on model predictions than clinical variables such as the Up-to-seven criteria, lung metastasis (LungMet), AFP level, and tumor size." (PMID 40517171, 2025). "While AFP is commonly used as a prognostic biomarker in HCC and is often associated with more aggressive tumor biology and advanced disease stage, its role in modulating immune response is not recognized." (PMID 40387836, 2025). "An important clinical presentation feature in Perú is tumor size, with a mean diameter of 14 cm and high levels of AFP, with 29,000 ng/ml/tumor-cm in younger and 4,300 ng/ml/tumor-cm in older patients." (PMID 40452835, 2025). "The levels of tumor markers, including AFP, carcinoembryonic antigen (CEA), carbohydrate antigen (CA) 12-5/19-9/72-4, and cytokeratin 19 (CK19), were all within the normal range." (PMID 40538841, 2025). "Globally, serum AFP level is commonly used as a tumor marker for HCC, whereas in Japan, the AFP-L3 fraction and DCP are also measured simultaneously." (PMID 40055288, 2025). "Clinical data (tumor diameter, AFP, GGT, differentiation grade, etc.)and HBP MRI images were collected." (PMID 41237121, 2025). "Elevated levels of these markers in cancer patients, along with their correlation with conventional (CEA and AFP) tumour markers, underscore their relevance in early cancer diagnosis and prognosis." (PMID 40821642, 2025). "Postoperatively, tumor markers normalized within two months (AFP 5.51 ng/mL, β-HCG <2.39 mIU/mL, HE4 39.7 pmol/L)." (PMID 41018086, 2025). "Regarding prognostic factors for recurrence, previous studies have identified tumor number, AFP response, tumor response, and successful downstaging as independent predictors of RFS." (PMID 40934000, 2025). "Future research should explore the potential applicability of this preset dilution factor strategy beyond obstetric testing—such as for tumor markers including Tg, AFP, CEA, and PSA." (PMID 40970183, 2025). "This study examined prognostic factors related to OS, such as age, ECOG performance status, tumor burden, AFP level, ALBI grade, and radiologic features, aligning with findings from prior research." (PMID 41199230, 2025). "This supports the utility of AFP response as a surrogate marker for tumor response, particularly when frequent imaging assessments are not feasible." (PMID 39941701, 2025). "The baseline AFP level before treatment directly reflects the biological invasiveness and overall burden of the tumor." (PMID 41463179, 2025). "The three patient groups showed differences in race, grade, T, N, M, tumor stage, AFP levels, and tumor size." (PMID 40308491, 2025). "Elevated AFP and increased tumor size are prognostic risk factors for HCC, and the combination of tumor burden and AFP serves as an important indicator of poor prognosis." (PMID 40857604, 2025). "GCTs are further characterized by varying serum tumor biomarkers, such as alpha-fetoprotein (AFP), human chorionic gonadotropin (hCG), and lactate dehydrogenase (LDH)." (PMID 39726664, 2025).
tumor (continued). "Elevated levels of DAP3 were correlated with larger tumor size and higher alpha-fetoprotein (AFP) levels, and Cox analysis confirmed that DAP3 was a clinically independent prognostic marker." (PMID 40051634, 2025). "The sensor demonstrates a sensitivity of 0.31 ng/mL and shows strong selectivity against other tumor markers like AFP and CA125." (PMID 39996991, 2025). "Serum tumor markers alpha-fetoprotein (AFP) and carbohydrate antigen 19-9 (CA19-9) also came out to be in the normal range." (PMID 40034887, 2025). "In a cohort liver transplantation after TACE, decreases of AFP after TACE and initial AFP were related to complete tumor necrosis in histologic examination." (PMID 40392828, 2025). "The pathologic stage, tumor status, gender, T stage, N stage, M stage, residual tumor, histologic grade, Child-Pugh grade, OS event, vascular invasion, age, AFP (ng/ml), and BMI were all included in the 374 HCC patients' clinical data." (PMID 38231074, 2025). "A previous study has shown that antigen processing and interferon-γ response–related genes are highly expressed in AFP-positive HCC tumor cells." (PMID 41451207, 2025). "In conclusion, we developed a simple and reliable scoring system to predict the efficacy and prognosis of immunotherapy in HCC patients based on two easily accessible clinic metrics: baseline AFP and initial tumor shape." (PMID 39714631, 2025). "Generally, the higher the AFP level is, the poorer the tumor differentiation is and the faster the growth rate is." (PMID 41463179, 2025). "Tumor markers, including alpha-fetoprotein (AFP) and beta-human chorionic gonadotropin (β-hCG), were elevated, raising concern for malignancy." (PMID 41384202, 2025). "Overall, this study provides new insights into the prediction of postoperative recurrence and underscores the importance of tumor size reduction and AFP level decline as dynamic indicators." (PMID 40934000, 2025). "Our results reinforce the importance of established prognostic factors—such as tumor size and baseline AFP levels—and demonstrate how these can be integrated into a risk-based scoring approach for HCC patients." (PMID 40308490, 2025). "Many centers now use selection criteria that include both numeric tumor burden (size and number) and alpha fetoprotein (AFP)." (PMID 40806987, 2025). "Tumor markers were markedly elevated: alpha-fetoprotein (AFP) of 1243.6 ng/mL (normal: 0–10.0 ng/mL) and protein induced by vitamin K absence or antagonist-II (PIVKA-II) of 809 mAU/mL (normal: 0–39 mAU/mL)." (PMID 41415330, 2025). "Based on this, we will investigate the predictive utility of baseline AFP and tumor shape for efficacy and prognosis in HCC patients receiving immunotherapy in this study." (PMID 39714631, 2025). "Higher AFP values suggest higher tumor burden and higher biological aggressiveness, thereby leading to pain, fatigue, and anorexia." (PMID 40385925, 2025). "This study focused on two widely used tumor markers in clinical practice: alpha-fetoprotein (AFP) and des-gamma-carboxy prothrombin (DCP)." (PMID 41463142, 2025). "The cAMP-PKA pathway and the induction of Ca2+ influx are necessary for the promotion of AFP/AFPR tumor proliferation." (PMID 41614820, 2025). "Serum tumor markers, including alpha-fetoprotein (AFP) and carcinoembryonic antigen (CEA), were within normal ranges." (PMID 40538841, 2025). "Several extended criteria are used clinically to address this limitation, including both morphological criteria (University of California, San Francisco—UCSF, up-to-seven) and those incorporating tumor biology surrogate AFP (AFP score, MetroTicket 2.0)." (PMID 39941867, 2025). "In BCLC 0/A, TARE-treated patients had higher median AFP levels (8.9 vs. 8.0, p = 0.046) and a larger maximum tumor diameter (4.2 [2.3–5.8] vs. 2.7 [1.8–3.7] cm, p = 0.001)." (PMID 40647551, 2025). "The model includes patients with the number of lesions <5, tumor size ≤5 cm, and AFP levels ≤500 ng/ml." (PMID 40709064, 2025).
tumor (continued). "Tumor markers of AFP and PIVKA-II are expected to play additional role along with imaging methods in HCC." (PMID 40392828, 2025). "Circulating tumour DNA (ctDNA) enables serial, minimally invasive detection of MRD and dynamic risk stratification that can outperform AFP alone and, in some series, predate imaging by months." (PMID 41301037, 2025). "The hazard ratios of CS subtypes were similar to the tumor stage, which is often used to evaluate the patient’s prognosis in the clinic and were significantly superior to those of AFP, albumin (ALB) and PT (P < 0.05)." (PMID 40771801, 2025). "Tumour markers, including alpha-fetoprotein (AFP), carcinoembryonic antigen (CEA), carbohydrate antigen 19-9 (CA19-9), and cancer antigen 125 (CA-125), were within normal ranges." (PMID 41426863, 2025). "Taken together, our data reinforce the diagnostic and clinical utility of AFP and β-HCG, while highlighting the potential role of inflammatory indices (NLR, MPV/PLT, and PLT×NLR) as supportive tools in assessing tumor biology." (PMID 41527642, 2025). "The alpha-fetoprotein (AFP) level was 2107 ng/ml, with the formation of a hepatic venous tumor thrombus (HVTT) in the right branch." (PMID 41573652, 2025). "When gonadal dysgenesis is confirmed, tumor markers such as alpha-fetoprotein,beta human chorionic gonadotropin, lactate dehydrogenase, and placental alkalinephosphatase should be considered." (PMID 40073224, 2025). "Clinical data analysis revealed that high METTL1 expression correlates significantly with larger tumor size, elevated serum AFP levels, tumor vascular invasion, and reduced survival rates." (PMID 40809384, 2025). "Second, the log-fold change in AFP reflects patient responsiveness to chemotherapy, while it cannot indicate the total tumor cell burden before LT." (PMID 40061426, 2025). "Sirolimus use for more than 3 months is an independent protective factor for improved survival, with benefits particularly significant in patients with high AFP levels and poorer tumor biology." (PMID 41375072, 2025). "Histopathological analyses, including H&E staining, IHC, and IF staining of the corresponding patient tumor tissues, confirmed that organoid #3 accurately recapitulated the expression patterns of key tumor-specific markers, such as AFP and CK18." (PMID 40750772, 2025). "Laboratory tests on admission revealed multiple, markedly elevated serum tumor markers: AFP (125.7 ng/mL; ref: <10.0), beta-hCG (10,534 mIU/mL; ref: <5.0), and CA 19-9 (1,017 U/mL; ref: <37)." (PMID 41384202, 2025). "AFP is not only the most widely used serological tumor marker in the diagnosis of HCC, but also its level is an independent and powerful predictor for evaluating the prognosis of patients." (PMID 41463179, 2025). "A notable feature of SHCC is the frequent observation of low or undetectable AFP levels, which can complicate early diagnosis and tumor monitoring." (PMID 41267711, 2025). "Univariate analysis revealed that the AFP level, tumor size, tumor number, TNM stage, vascular invasion, satellite lesions, and RGS14 expression were significantly associated with OS in HCC patients." (PMID 40312502, 2025). "Conversely, overexpression of USP13 using AAV8-USP13 in mice produced the opposite effects: tumor volume significantly increased, AFP levels were elevated, and the infiltration of CD8 + T cells was notably reduced." (PMID 41330897, 2025). "Laboratory investigations revealed elevated liver enzymes and tumor markers, including AFP, at 24 502 ng/mL." (PMID 40922714, 2025). "High expression of CCAT1-70aa correlates significantly with tumor pathological staging, serum AFP concentration, and vascular invasion." (PMID 40918165, 2025). "Tumour-informed serial monitoring in real-world cohorts demonstrates earlier molecular recurrence than AFP or imaging, with clinically actionable lead times of approximately 7.9 months." (PMID 41301037, 2025).
tumor (continued). "Of note, several scoring systems that were reported to differentiate post-transplant survival successfully have incorporated AFP into tumor size/numbers." (PMID 40427147, 2025). "AFP inhibits immune responses and remodels the tumor microenvironment through various mechanisms, further suppressing antitumor immunity." (PMID 40458724, 2025). "High serum AFP levels demonstrated an association with MVI, poor differentiation, and prediction of tumor recurrence after hepatectomy and transplantation." (PMID 40866831, 2025). "Tumor markers, including alpha-fetoprotein (AFP), carbohydrate antigen (CA199), and carcinoembryonic antigen (CEA), were within normal ranges." (PMID 40859536, 2025). "Approximately half had AFP >400 ng/mL, and most presented with multiple tumors, with tumor size >10 cm observed in 31.5% and 49.1% of patients." (PMID 41376633, 2025). "A Kruskal-Wallis analysis was conducted to evaluate differences in tumor marker levels among the cigarette type groups, including AFP, CA 19-9, CEA, and PSA." (PMID 40078230, 2025). "Significantly different expressions of DBF4B were observed in various clinical features of LIHC, including pathological stage, tumor status, ethnicity, body weight, histological type, histological grade, alpha-fetoprotein, and vascular infiltration." (PMID 40535802, 2025). "Regarding tumor markers, elevated AFP levels were observed in 28.8% of patients, which is lower than the previously reported 50%17." (PMID 41210683, 2025). "Imaging after eight and 12 cycles demonstrated marked tumor regression and the normalization of AFP (<2 ng/mL), confirming a diagnosis of pseudoprogression." (PMID 40726876, 2025). "The female tumor marker panel revealed a markedly elevated alpha-fetoprotein (AFP) level of 792.1 ng/mL (reference range: 0–7 ng/mL)." (PMID 40602768, 2025). "Feature importance rankings (T stage > Tumor size > AFP) correspond closely with established molecular mechanisms governing HCC metastasis and survival outcomes." (PMID 40718824, 2025). "Tumor markers, including AFP, CEA, CA19-9, CA-125, and CA15-3, are routinely used for the diagnosis and surveillance of cancer." (PMID 41291551, 2025). "We then performed a univariable and multivariable Cox regression analysis of OS and PFS using known factors that impact survival outcomes, including aetiology, BCLC stage, serum AFP and tumour size." (PMID 40596669, 2025). "Consistent with previous analyses, higher levels of pretreatment AFP, NLR, AAR, ALBI score, SII, and decreased CALLY index and N/CRP ratio were associated with the presence of vascular invasion and last tumor size." (PMID 40181742, 2025). "The findings of this study revealed that elevated AIDRS score were associated with a more unfavorable prognosis for HCC patients with larger tumor volumes, elevated AFP, and longer PT." (PMID 40771801, 2025). "The maximal tumor size, alpha fetoprotein level, and treatment modality were independent predictors for OS, while the maximal tumor size and treatment modality were independent determinants for PFS." (PMID 40406260, 2025). "Among tumor markers, serum α-fetoprotein (AFP) and prothrombin induced by vitamin K absence-II (PIVKA-II) are known as useful factors for the diagnosis and surveillance in HCC." (PMID 40392828, 2025). "By incorporating variables such as tumor size, vascular invasion, and serum alpha-fetoprotein levels, these models provide a comprehensive assessment of recurrence risk, with an independent external cohort being used to validate the results." (PMID 41008847, 2025). "Building on prior findings, our study further explored the impact of tumor size reduction and AFP decline ratio on postoperative recurrence during conversion therapy." (PMID 40934000, 2025). "Conversely, in the low-tumor-marker group (post-treatment AFP ≤ 10 ng/mL), AFP levels decreased slightly from 2.8 ng/mL to 2.1 ng/mL, but this change was not statistically significant (p = 0.552)." (PMID 40002160, 2025).